TRAJ8 (T cell receptor alpha joining 8)
Gene: Gene (Ensembl biotype TR_J_pseudogene) on chromosome 14 (22,536,145 to 22,536,204, forward strand). Ensembl gene ENSG00000211881.
Diseases named in the same sentence as TRAJ8 in open-access papers:
TRAJ8 is named in the same sentence as 1 disease in open-access papers, as found by Europe PMC text mining. Sharing a sentence is not in itself a finding about the gene and the disease. The quoted sentences say what the papers report.
tumour (1 paper, 2018). "Here we show that the structures of two distinct TCRs (TRAV4+TRAJ21+-TRBV28+TRBJ2-3+ and TRAV4+TRAJ8+-TRBV9+TRBJ2-1+), originating from a polyclonal T-cell repertoire, bind to HLA-B*07:02, presenting a 13-amino-acid-long tumour-associated peptide, NY-ESO-160–72." (PMID 29531227, 2018).